CD44 (CD44 molecule (IN blood group))
Diseases named in the same sentence as CD44 in open-access papers (continued):
Sharing a sentence is not in itself a finding about the gene and the disease.
colon carcinoma (continued). "CD44-overexpressing cells have been reported to increase EMT-like changes in vitro and decrease the E-cadherin expression, while inducing the expression of EMT markers in colon cancer cells." (PMID 33071648, 2020). "Furthermore, as a transmembrane glycoprotein, CD44 plays the key role in CRC cell adhesion, migration, and metastasis as well as in the EMT-like modifications in colon cancer cells." (PMID 33071648, 2020). "Moreover, western blot and qRT-PCR results showed BCAR4high cells showed higher expression of NANOG, OCT4, SOX2, CD44, CD133 and Lgr5 which are important markers of CSC in colon cancer." (PMID 30962766, 2019). "In addition, we found increased expression of stem cell markers, including OCT4, Lin28, KLF, Bmi-1, CD44 and SOX2, in colon cancer cells upon treatment of BM-MSC-derived exosomes." (PMID 30220706, 2018). "Colon cancer stem cells are identified by expression of CD133, CD44, CD26 and Lgr5, although some data suggests this profile may be modulated during metastasis, ex vivo cell manipulation, or passage in culture." (PMID 29899829, 2018). "Importantly, spheroid cultures of these colon cancer stem cells contain an expression of other stem cell markers, such as LGR5, CD44, nuclear β-catenin and CD166." (PMID 29652830, 2018). "Finally, analysis of the gene expression in stage IV of colon cancer showed a strong correlation between EVI1 and E-CADHERIN, N-CADHERIN and CD44." (PMID 29339729, 2018). "The resistance in CSCs is often correlated to the CSC surface marker profiles; CD44+High and CD133+High cells are highly radio-resistant in colon cancer and they have a higher DNA repair capacity and ability to escape apoptosis compared to CD44Low and CD133Low CSCs27." (PMID 28536422, 2017). "Various colon cancer cell lines were screened for CD133 and CD44 expression." (PMID 26840024, 2016). "Moreover, we determined CD44/CD24 expression for breast and CD44/CD133/CD326 expression for colon cancer cell lines to study the proportion of cancer cells with a CSC phenotype in the different subpopulations." (PMID 26752044, 2016). "In addition, we will collect colon cancer patient samples and investigate the expression level of CD133 and CD44." (PMID 26840024, 2016). "Furthermore, protein expression of SMO, Gli1, CD44, and CD133 was decreased in colon cancer cells in response to treatment with the SMO inhibitor cyclopamine." (PMID 27894099, 2016). "Seven human colon cancer cell lines were analyzed for CD133 and CD44 expression on their surface." (PMID 27659530, 2016). "Therefore, the significant levels of CD133 and CD44 found in HCT-116 cells are concurrent with the aggressive cancer properties such as tumor proliferation and metastasis that these cells display in colon cancer." (PMID 26840024, 2016). "Our recent work confirmed that CD44-positive colorectal adenoma cell growth and survival depend on autocrine FGF18/FGFR3-IIIc signaling, thus indicating importance of this pathway already in precursor lesions of colon cancer." (PMID 27650542, 2016). "MiR-373 is an oncogene and can induce tumor initiation and progression in testicular germ-cell tumors by targeting tumor suppressor LATS2, and invasion and metastasis by targeting CD44, RECK, mTOR and SIRT1 in breast, colon cancer and fibrosarcoma, respectively." (PMID 26258411, 2015). "Overexpression of CD44 has also been shown to promote resistance to etoposide-induced apoptosis by alteration of levels of caspase 9, caspase 3, Bcl-xl, and Bak, down-regulation of pRB, and phosphorylation of AKT in colon cancer." (PMID 25823654, 2015). "In the present study, we aimed to validate the single biomarkers CD44 rs8193 C>T, ALCAM rs1157 G>A and LGR5 rs17109924 T>C based on our preliminary findings in a large and independent study cohort of 742 stage II and III colon cancer patients." (PMID 25665511, 2015).
colon carcinoma (continued). "Taken together, these results clearly indicated that both HIF-1α and HIF-2α play key roles in promoting the in vivo aggressiveness and tumor growth of both CD44+ and CD44−/CD133− subpopulations isolated from SW480 colon cancer cells, which exhibit constitutively active Wnt signaling." (PMID 25396735, 2014). "In summary, the three colon cancer cell lines had a varying expression of CD133, CD44 and CD24." (PMID 24760019, 2014). "The CD133 expression was reduced in the AKT1 KO but not AKT2 KO colon cancer cell line, whereas the expression of CD44 was increased by both AKT1 KO and AKT2 KO." (PMID 24760019, 2014). "It has been suggested that CD44, CD24, and CD133 are hallmarks for colon cancer stem cells (CCSCs)." (PMID 24696849, 2014). "To further assess Wnt upregulation, we performed qRT-PCR analysis using total RNA isolated from the colonic tumors of APCMin and APC-Cldn1 and detected increased mRNA expression of the established Wnt-target genes CD44 (p = 0.0159), Lgr5 (5-fold increase), and Axin2 (3-fold increase)." (PMID 24997475, 2014). "In this context, we compared CD44-positive colon cancer cells that did not contain the vriant exon 9 and those that did." (PMID 23800986, 2013). "By immunopurifying CD44 from PDGF-treated and untreated LS174T colon carcinoma cells, which express predominantly CD44v, and HL60 myeloid cells, which exclusively express CD44s, we demonstrated the divergent effects of PGDF on CD44v versus CD44s binding to fibrin." (PMID 23056168, 2012). "Of note, incubation of LS174T colon carcinoma cells with PDGF (100 ng/ml) did not affect the surface expression levels of CD44, as assessed by flow cytometry (data not shown)." (PMID 23056168, 2012). "Interestingly, curcumin with or without 5-fluorouracil and oxaliplatin significantly reduced the number of cells showing CSC-markers CD44 and CD166 in a colon cancer cell line that had survived previous treatment with 5-fluorouracil." (PMID 23095512, 2012). "Homozygous CD44 deletion affected intestinal crypt cell survival and attenuated tumorigenecity without affecting proliferation in a primary mouse colon carcinoma model." (PMID 21124918, 2010). "Interestingly, even though treatment of the xenografts with irinotecan, a chemotherapeutic often used in colon cancer, slowed down tumor growth, the frequency of ESA+CD44+CD166+ cells and the clonogenicity was increased." (PMID 21311095, 2010). "In addition, overexpression of at least two peptides corresponding to CD166, CD44, CD29, CEACAM5, biglycan, and cadherin 17 was detected in the colon tumour spheres." (PMID 20332776, 2010). "Some sources suggest that CD44 and CD18 may colocalize to mediate lymphocyte rolling and adhesion and that CD44 interacts with the β2 subunit (CD18) of the LFA-1 integrin in lymphocytes and in colon cancer cells." (PMID 38983848, 2024). "Interestingly, CD44, a well-established COREAD protein, was upregulated only in rectal tumors showing its potential to distinguish rectal from colon carcinomas." (PMID 37384253, 2023). "Furthermore, DPEP1 also could enhance the expression of colon cancer stem cell markers (LGR5, CD133, and CD44), which strengthened the tolerance of colon cancer cells to chemotherapy drugs." (PMID 35670012, 2023). "In addition, a cell-type restricted activity of hnRNPM has been revealed as it does not promote CD44 exon skipping in HCT116 human colon cancer cells." (PMID 38106992, 2023). "To further verify whether TP5 promotes the antitumor effect of OXA by inhibiting colon cancer stem cells, we measured the expression of cancer stem cell markers CD24 and CD44 by flow cytometry after TP5 and OXA were co-administered to colon cancer HCT116 cells for 24 h." (PMID 35242031, 2022).
colon carcinoma (continued). "Specifically, two highly invasive colon cancer cell lines, HCT116 and HT29, were evaluated in the present study, as a previous study reported that these cell lines harbor minority cell populations with the highest observed expression of CD133, which coincided with high CD44 expression." (PMID 33819194, 2021). "Thus, using an 89Zr labeled Ab that cross-reacts with both human and mouse CD44, we demonstrate that CD44 immuno-PET has the capacity to monitor CD44 regulation on splenic myeloid cells and may also be useful for imaging colon tumors." (PMID 33594192, 2021). "Furthermore, in colon cancer, the internalized CD44 and acetyltransferase p300 induce STAT3 acetylation at Lysine (Lys) 685, which in turn promotes the expression of cell cycle regulators cyclin D1 70, MYC, and Twist1 in colon cancer cells." (PMID 32754274, 2020). "In HCT116 and HT29 cells, CD133+CD44+ cells not only shared the extensive tumorigenic potential of LT-TICs but also functionally reproduced the behaviors of LT-TICs that drive tumor metastasis (TM) formation, suggesting that CD133+CD44+ cells are a typical representation of LT-TICs in colon cancer." (PMID 32729895, 2020). "Thus, based on the functional role of CD133+ and CD44+ cells in colon cancer (see introduction), we hypothesized that, similar to the functional characteristics of LT-TICs, CD133+CD44+ cells also possessed the capacity to drive TM." (PMID 32729895, 2020). "Thus far, CD44, CD133, and CD166 were shown to represent informative CSC markers in colon cancer." (PMID 30804456, 2019). "It is interesting to note that in agreement with this, in our study we found that under normal culture conditions, primary SW480 colon cancer cells express the CD44 stem marker and do not express CD133, whereas their derivative metastatic SW620 cell line mainly expresses CD133." (PMID 31139149, 2019). "Notably, as PES1 is up-regulated by CD44, c-Jun, and BRD4 in liver or colon cancer cells." (PMID 31718704, 2019). "Moreover, CD44 and CD166 expression can also be used to enrich for a CSC subset in colon cancers." (PMID 28573140, 2017). "Therefore, CD44 and CD24 could be used as markers for selecting colon cancer stem cells from SW480 cells, LOVO cells, and HCT116 cells by MACS." (PMID 24696849, 2014). "In a study, curcumin supplementation significantly reduced the expression of CD44 and the number and size of tumor sphere formation of colon cancer HCT-116 and HCT-8 cells, which indicated that curcumin could inhibit the stem-cell like characteristics in colon cancer cells." (PMID 36009200, 2022). "Therefore, the expression of CD44 and CD133 on colon carcinoma (HT-29) cells was analyzed using flow cytometry after the permeation of the cells through NM-11 and PLGA/SK filters, where colon carcinoma cells expressing CD133 and CD44 are typically considered CSCs (CICs)." (PMID 34641226, 2021). "In addition, we further analyzed whether PRDX2 transcriptional levels correlate with CD133 and CD44 expression in 40 pairs of human colon carcinomas with matched adjacent noncancerous tissues (ANTs)." (PMID 33819194, 2021). "Furthermore, we demonstrated that chitosan might activate canonical Wnt/β-catenin-CD44 axis signaling in CD44positive colon cancer cells and noncanonical Wnt-STAT3 signaling in CD44negative HCC cells." (PMID 28367998, 2017). "Nevertheless, in our study, we found that the suppression of G13D mutation promoted major stem markers like CD133, Lgr5, and TGF-β but not others like CD44 and CD24, which were reported as common and important biomarkers for colon cancer by us and others." (PMID 36386200, 2022).
colon carcinoma (continued). "For CSCs, there is no unique biomarker to identify them, for instance, in colon cancer, the most popular biomarkers are some surface adhesion molecules like CD24, CD44, and CD133." (PMID 36386200, 2022). "As many as 5 × 106 HCT116- or HT29-CD133−CD44− colon cancer cells did not induce tumor formation, but as few as 1 × 103 CD133+CD44+ cells generated visible tumors after 4 weeks." (PMID 32729895, 2020). "The phenotypic analysis revealed that, in contrast to CD133, CD44, CD66c and CD26, are reliable markers of CTCs in colon cancer patients (data not shown)." (PMID 25624884, 2015). "We further probed the expression of Nodal ligand and its receptors in CD44-negative as well as CD24-positive and -negative colon cancer cells." (PMID 24696849, 2014). "Using MACS, we selected CD44- and CD24-positive and -negative colon cancer cells from SW480 cells, LOVO cells, and HCT116 cells." (PMID 24696849, 2014). "Significantly, we revealed that Nodal transcript and protein were absent in CD44- and CD24-negative colon cancer cells, whereas it is present in CCSCs, implicating that Nodal is required for maintaining stemness of colon cancer stem cell." (PMID 24696849, 2014). "We recently reported that CD44 is the primary fibrin, but not fibrinogen, receptor on LS174T colon carcinoma cells." (PMID 23056168, 2012). "In this study we found that in colon cancer cells the inhibition of OGT or the exposure of cells to an acute nutritional stress mimicking the lack of OGT, induce the appearance of an aggressive CD133/CD44 double positive CSC subpopulation." (PMID 31139149, 2019). "Furthermore, qRT-PCR analysis for Wnt target genes (including cMyc, Ascl2, Axin2, CD44, CD1, Sox17, Wif1 and Tiam1) did not identify any significant differences between the colonic tumours isolated from both cohorts of mice." (PMID 25881306, 2015). "However, recent studies by others have shown that NANK, a human colon tumor cell line with a high level of Bmi-1 expression but negative for CD133, CD44, Oct4, and Nanog, is capable of initiating tumors in mice." (PMID 23174018, 2012). "A doxorubicin hydrochloride (Dox) loaded CD44-targeted drug delivery system based on hyaluronic acid modified mesoporous silica nanoparticles (MSNs) has been developed and shown greater cytotoxicity to HCT-116 (human colon cancer cells) than free Dox and nontargeted MSNs." (PMID 26569228, 2015). "In addition, in another public transcript data set (GSE76342) for the colon cancer cell line LoVo with or without metformin treatment, we found that metformin inhibited expression of the CSC markers Lgr5, ASCL2, EPHB3, OLFM4, BMI1, Lrig1, TERT, CD44, and CD133." (PMID 32911743, 2020).
pancreatic cancer (299 papers, 2005 to 2026). "Pancreatic cancer stem cells (PaCSCs) are maintained by specific surface markers (CD44, CD133, EpCAM, ALDH1A1) and regulated by stemness-associated signaling pathways such as Wnt/β-catenin, Notch, Hedgehog, and TGF-β." (PMID 40881675, 2025). "For PANC-1, we assessed CD24, CD44, and EpCam since these have been linked with a more specific phenotype for CSCs in pancreas cancer." (PMID 38542325, 2024). "HA has significant implications in pancreatic cancer through its interactions with CD44 and has been associated with pancreatic cancer cell growth." (PMID 39830124, 2024). "CD44 is a cell-surface glycoprotein involved in cell–cell interactions, and its high transcript level in pancreatic cancer tissues, which is linked to a poor survival rate for patients with pancreatic cancer, was shown in the TCGA database." (PMID 37699930, 2023). "It has been reported that the expression of CD44 variants significantly correlates with poor prognosis in patients with colon or pancreatic cancer." (PMID 37108495, 2023). "Pancreatic CSCs (PCSCs), that represent approximately 0.5-1% of pancreatic cancer cells, are characterized by the expression of the surface markers CD44+/CD24+, CD133+ and ESA+, and their presence is associated with poor prognosis." (PMID 36776295, 2023). "The expression of CD44 variants showed a significant correlation with poor prognosis in colon and pancreatic cancer." (PMID 37108495, 2023). "The extract also inhibited CD44+/CD24+/EpCAMhigh pancreatic cancer stem cell (CSC) populations, CSC-associated markers SOX2, OCT4, NANOG and CD44 in-vitro and in-vivo, and increased sensitivity to gemcitabine." (PMID 32726914, 2020). "Our lab showed that a flow sorted pancreatic cancer cell population (CFPAC1-CD44Low cells) that expressed low levels of CD44s but with expression of multiple CD44 variant isoforms also expressed higher levels of ALDH." (PMID 29747682, 2018). "Downregulation of miR-205 results in increased expression of stem cell markers OKT3, OKT8, and CD44 in pancreatic cancer tissue and is linked to gemcitabine resistance." (PMID 29967761, 2018). "The finding in the present study that CD44 expression correlates with a favorable prognosis in pancreatic cancer can be explained by the fact that there is a significant association between CD44 expression and lymph node metastasis." (PMID 26666511, 2015). "We then detected the expression levels of all CD44 variants in the three pancreatic carcinoma cell lines." (PMID 24708709, 2014). "We demonstrated that among all CD44 variants, CD44v6+, CD44v9+ and CD44s− were significantly associated with the metastasis and prognosis of pancreatic carcinoma." (PMID 24708709, 2014). "In addition, previous studies have demonstrated that KDM5A and KDM5C are overexpressed in gemcitabine-resistant pancreatic cancer cells and that their expression is regulated by CD44, a stem cell marker linked to chemoresistance." (PMID 39239542, 2024). "In addition, studies have suggested the critical role of the SPP1 – CD44 axis between macrophages and glioma cancer cells and between cancer-associated fibroblasts and pancreatic cancer cells." (PMID 39691723, 2024). "Similarly, in pancreatic cancer, CD44-expressing CSCs are implicated in resistance to standard chemotherapy regimens." (PMID 39518076, 2024). "We also found that dormancy is a hallmark of cancer stem cells with respect to cancer recurrence, and the association of C4orf47 expression with CD44 expression may be involved in the maintenance of pancreatic cancer stem cells." (PMID 36741255, 2023). "In this study, we evaluated the effect of 1,2,3,4,6-penta-O-galloyl-β-D-glucose (PGG), a gallotannin contained in various medicinal plants, on CD44 standard (CD44s) and CD44 variant 3 (CD44v3) in Mia-PaCa-2, human pancreatic cancer cells and explored the underlying mechanisms." (PMID 36605595, 2022).